VENTX (VENT homeobox)
Diseases named in the same sentence as VENTX in open-access papers:
VENTX is named in the same sentence as 30 diseases in open-access papers, as found by Europe PMC text mining. Sharing a sentence is not in itself a finding about the gene and the disease. The quoted sentences say what the papers report.
colon cancer (4 papers, 2016 to 2023). "To determine the effects of VentX on the growth of other solid tumors in which aberrant Wnt signaling has been implicated, we tested the effects of VentX on the growth of HCT116 colon cancer cells and H460 lung cancer cells." (PMID 27175592, 2016). "Using a NSG mouse model of human colon cancers, we demonstrate that VentX regulates TAM function in tumorigenesis in vivo." (PMID 29872044, 2018). "Using a NOD scid γ (NSG) mouse model of patient-derived xenograft (NSG-PDX) of colon cancers, we showed that VentX-modulated-TAMs function in tumorigenesis in vivo." (PMID 29872044, 2018). "An ex vivo study found that VENTX expression was significantly reduced in TAM of colon cancer patients, which could drive the intracellular signaling pathway TAM toward M1 phenotype, reversing immunosuppression in the tumor microenvironment and regulating TAM plasticity and immune status." (PMID 37894938, 2023).
acute myeloid leukemia (3 papers, 2016 to 2024). Acute myeloid leukemia (AML) is a group of neoplasms arising from precursor cells committed to the myeloid cell-line differentiation. "Recently, we identified the physiological expression of the NKL-subclass homeobox gene VENTX exclusively in cDCs and the aberrant expression in acute myeloid leukemia (AML)." (PMID 38474011, 2024). "Aberrant activities of particular NKL homeobox genes have been described in myeloid malignancies as well, exemplified by DLX2, HLX and VENTX in acute myeloid leukemia (AML)." (PMID 31825998, 2019). "The human Vent-like homeobox gene VENTX, a putative homolog of the Xenopus laevis Xvent-2 gene, was shown to be highly expressed in normal myeloid cells and in patients with acute myeloid leukemia." (PMID 27888632, 2016). "The leukemogenic potential of VENTX was confirmed in the AML1-ETO transplantation model, as in contrast to AML1-ETO alone co-expression of AML1-ETO and VENTX induced acute myeloid leukemia, partly expressing erythroid markers, in all transplanted mice." (PMID 27888632, 2016).
leukemia (3 papers, 2016 to 2022). A malignant (clonal) hematologic disorder, involving hematopoietic stem cells and characterized by the presence of primitive or atypical myeloid or lymphoid cells in the bone marrow and the blood. "The rationale for this was that we have seen high expression of VENTX in patients with AML1-ETO positive leukemia among others before." (PMID 27888632, 2016). "VENTX and NANOG are highly expressed in CD34+ leukemic stem cells (LSC, a subpopulation responsible for drug resistance, metastasis, and leukemia relapse) and their depletion blocks AML proliferation and growth." (PMID 35892595, 2022). "Interestingly, VENTX and NANOG share activity in hematopoiesis by repressing the genes responsible for terminal differentiation (e.g., TAL1, KLF1), as well as promoting leukemia." (PMID 35892595, 2022). "Constitutive expression of VENTX in normal CD34+ human progenitor cells impaired lymphoid engraftment and fostered generation of myeloid cells, but failed to induce leukemia in vivo." (PMID 27888632, 2016).
gastric cancer (2 papers, 2023 to 2025). A primary or metastatic malignant neoplasm involving the stomach. "In this study, we systematically delineated the transcriptional regulatory landscape of THY1 in gastric cancer by identifying six robust putative regulators—PRRX1, TWIST1, SNAI2, MEIS3, VENTX, and EGR2—through an integrative multicohort approach." (PMID 40476057, 2025).
germ cell tumor (2 papers, 2012 to 2016). A benign or malignant, gonadal or extragonadal neoplasm that originates from germ cells. "We found a correlation between PIM1/2 expression and VENTX, SOX15, UTF1, NANOG, POU5F1P4, POU5F1P3, and POU5F1B expression in male germ cell tumors." (PMID 27901106, 2016).
glioma (2 papers, 2021 to 2022). A benign or malignant brain and spinal cord tumor that arises from glial cells (astrocytes, oligodendrocytes, ependymal cells). "Intriguingly, VENTX is important for the proliferation of neural stem cells (NSCs), Glioma, and Glioblastoma, thus suggesting an important role for VENTX both in normal/physiological and abnormal conditions of the human brain." (PMID 35892595, 2022). "Cell-cycle related pathways were downregulated and transcriptional regulation by VENTX was upregulated in grade 3 glioma and GBM." (PMID 34205437, 2021). "VENTX and NANOG were found highly expressed in brain (glioma/glioblastoma), pancreatic renal, esophageal and testicular cancers." (PMID 35892595, 2022).
lymphocytic leukemia (2 papers, 2011 to 2016). "Its expression is downregulated in lymphocytic leukemias, suggesting a potential role of VENTX in the clinical behavior of hematopoietic malignancies." (PMID 21304903, 2011). "Expression analysis showed that VentX expression is reduced in lymphocytic leukemia, which led to the hypothesis that VentX functions as a tumor suppressor in lymphocytic leukemia." (PMID 27175592, 2016).
acute leukemia (1 paper, 2016). A clonal (malignant) hematopoietic disorder with an acute onset, affecting the bone marrow and the peripheral blood. "In our current bone marrow transplantation model, aberrant expression of VENTX was able to induce acute leukemia in a part of transplanted mice after long latency, indicating that VENTX needs collaborative partners to exert its full leukemogenic potential." (PMID 27888632, 2016).
brain cancer (1 paper, 2022). A primary or metastatic malignant neoplasm affecting the brain. "Survival rate based on VENTX expression levels suggests that VENTX may be used in the prognostic of brain cancer development and patient survival as well." (PMID 35892595, 2022).
chronic lymphocytic leukemia (1 paper, 2016). "Furthermore, the same group previously demonstrated that VENTX is able to impair cell growth in chronic lymphocytic leukemia." (PMID 27888632, 2016).
erythroblastic leukemia (1 paper, 2016). "Indeed, the most surprising observation was that VENTX induced expansion of primitive erythroid cells up to erythroblastic leukemia on its own and induced AML with partly erythroid features together with AML1-ETO." (PMID 27888632, 2016).
erythroleukemia (1 paper, 2016). Acute erythroid leukemia characterised by the presence of at least 50% erythroid precursors and at least 20% myeloblasts in the bone marrow. "Transplantation of bone marrow progenitor cells retrovirally engineered to express VENTX caused massive expansion of primitive erythroid cells and partly acute erythroleukemia in transplanted mice." (PMID 27888632, 2016). "VENTX was highly expressed in patients with primary human erythroleukemias and knockdown of VENTX in the erythroleukemic HEL cell line significantly blocked cell growth." (PMID 27888632, 2016).
glaucoma (1 paper, 2024). Increased pressure in the eyeball due to obstruction of the outflow of aqueous humor. "Regulation by the homeodomain transcription factor, VENTX, was the most significantly enriched gene set for IOP genes, which has not yet been associated with glaucoma." (PMID 38195602, 2024).
Insulin resistance (1 paper, 2019). Increased resistance towards insulin, that is, diminished effectiveness of insulin in reducing blood glucose levels. "Prostate androgen-regulated mucin-like protein 1 (PARM1), ALDH4A1, VENTX, and KIAA0040 are novel biomarkers for the development of insulin resistance." (PMID 30678306, 2019).
pancreatic cancer (1 paper, 2023). "In addition, VENTX expression has been found to promote phagocytosis and immunity in pancreatic cancer, and VENTX-modulated TAM has a strong inhibitory effect on tumorigenesis in vivo." (PMID 37894938, 2023).
prostate carcinoma (1 paper, 2016). A carcinoma that arises from epithelial cells of the prostate gland. "As VentX is an antagonist of the Wnt signaling implicated in prostate cancers, we sought to determine the potential effects of VentX on the growth of prostate cancer cells." (PMID 27175592, 2016). "VentX resides in chromosome 10q26, a region that is distal to the Pten, a tumor suppressor that is frequently deleted in advance prostate cancers." (PMID 27175592, 2016). "Our data showed that ectopic expression of VentX suppressed the growth of prostate cancer cells." (PMID 27175592, 2016).
renal carcinoma (1 paper, 2022). A carcinoma arising from the epithelium of the renal parenchyma or the renal pelvis. "As we expected, both of these drugs significantly decreased the proliferation rate of tumor cells and the expression levels of HOXC5, ISL1, and VENTX in two renal cancer cell lines." (PMID 35853872, 2022).
sarcoma (1 paper, 2021). A usually aggressive malignant neoplasm of the soft tissue or bone. "We can only hypothesise that VENTX downregulation may have played a role in altering the composition of the TME in this case and may be a potential therapeutic target in sarcomas associated with immune cell content." (PMID 33436720, 2021). "Differentially methylated regions and genes were detected, not been previously implicated in sarcoma progression, including at PTPRN2 and DAXX in LMS, WT1-AS and TNXB in SS, VENTX and NTRK3 in pleomorphic RMS and MEST and the C14MC / miR-379/miR-656 in MFS." (PMID 33436720, 2021).
tumor (11 papers, 2012 to 2025). "Down-regulated VentX expression in tumor associated macrophages (TAMs) underlies phagocytotic anergic phenotype of TAMs, which govern immunological state of TME." (PMID 38299030, 2024). "More recently, we characterized immunological state of primary human samples of colorectal cancer (CRC) and pancreatic ductal adenocarcinoma (PDAC) and found that down-regulated VentX expression in tumor associated macrophages (TAMs) underlies the immune suppression of CRC and PDAC TME." (PMID 38299030, 2024). "Genes such as APOE, TREM2, VENTX, and C1QA are associated with tumor growth and progression, promotion of apoptosis, and inflammation." (PMID 38910324, 2024). "We found that the restoration of VentX expression in TAMs promotes the polarization of NSCLC-TAMs from the pro-tumor M2-like phenotype to a more anti-tumor M1-like phenotypes." (PMID 38299030, 2024). "Our current study suggests the role of VentX-regulated-TAMs in promoting the efficacy of ICIs against solid tumors through mechanisms of tumor-specific activation of cytotoxic lymphocytes." (PMID 38299030, 2024). "The homeobox protein VENTX is antagonist of the Wnt signalling pathway and has shown to be dysregulated in the immune cells of the tumour microenvironment (TME), being a potential target for immunotherapy (Reviewed in68)." (PMID 33436720, 2021). "Here the authors show that the homeobox protein VentX is downregulated in clinical samples of colorectal cancer and regulates TAMs plasticity with its forced re-expression converting TAMs into an anti-tumor phenotype." (PMID 29872044, 2018). "Consistent with the results of over expression studies, the M1-TAMs transfected with control-MO exerts strong inhibition of tumor growth, but the inhibition was abolished by knocking-down VentX expression with VentX-MO." (PMID 29872044, 2018). "Our recent studies identified VentX, a homeobox transcriptional factor, as a putative tumor suppressor." (PMID 27175592, 2016). "All these data indicate that the function of VENTX largely depends on the cellular context and that VENTX can act as tumor suppressor and as oncogene." (PMID 27888632, 2016). "Using reverse-genetic approaches, our recent studies identified VentX as a novel Wnt antagonist and a putative tumor suppressor in hematopoietic malignancies." (PMID 27175592, 2016). "H&E staining and in situ apoptosis analysis by TUNEL staining showed that tumors expressing VentX displayed a large amount of fragmented DNA, suggesting that VentX represses tumor growth in vivo by inducing apoptotic cell death." (PMID 27175592, 2016). "On a more mechanistic level, we showed that the restoration of VentX expression in TAMs promotes TAM phagocytosis, which in turn promotes the tumor-specific activation of CD8 T cells." (PMID 38299030, 2024). "In this study, we revealed several pivotal regulatory TFs (HOXC5, ISL1, VENTX, and OTP) in tumor cells by integrating scRNA-seq and scATAC-seq data and further experimentally validated their roles in tumor growth." (PMID 35853872, 2022). "We identified tumor cell-specific regulatory programs mediated by four key transcription factors (TFs) (HOXC5, VENTX, ISL1, and OTP), and these TFs have prognostic significance in The Cancer Genome Atlas (TCGA) database." (PMID 35853872, 2022).
tumor (continued). "We showed that the restoration of VentX expression in TAMs reignites the phagocytotic function of TAMs, which in turn, transforms TIME, activates CTLs in a tumor-specific manner and promotes efficacy of PD-1 antibody against NSCLC but not toxicity on normal lung epithelial cells." (PMID 38299030, 2024). "As VentX has been shown to modulate phagocytosis, to elucidate the mechanisms of VentX-TAM in promoting efficacy of PD-1 antibody against NSCLC, we hypothesized that VentX promotes NSCLC-TAM phagocytosis of NSCLC tumor cells, which in turn, promotes CD8 T cell activation in a cancer-specific manner." (PMID 38299030, 2024).
cancer (8 papers, 2011 to 2025). A tumor composed of atypical neoplastic, often pleomorphic cells that invade other tissues. "Currently, the cause of decreased VentX expression in TAMs and the potential clinical application of VentX-modulated TAMs in cancer treatment remain to be further defined." (PMID 29872044, 2018). "Ectopicexpression of VentX, a transactivator of p16INK4a, has recentlybeen shown to cause senescence in cancer cells.Corresponding to our results, these authors show that both p21CIP1/WAF1and p16INK4a are involved in permanent cell cycle arrest." (PMID 22206000, 2011). "The role of VentX in immunopathogenesis of cancer was first indicated by our findings that VentX expression is down-regulated in TAMs." (PMID 38299030, 2024). "Whereas NANOG function has been extensively characterized in cancers, mainly for its expression and activity in cancer stem cells (CSCs), less is known about VENTX." (PMID 35892595, 2022). "The current study shows that VentX exerts strong inhibitory effects on the proliferation and survival of cancer cells derived from solid tumors." (PMID 27175592, 2016). "Our current studies show that VentX exerts strong inhibitory effects on the growth of cancer cells derived from solid tumors, similar to its effects on hematopoietic malignancies." (PMID 27175592, 2016). "VentX promotes phagocytosis of both cancer and normal epithelial cells." (PMID 38299030, 2024). "Thus, the BioGRID Open Repository of CRISPR screens (BioGRID-ORCS database) shows that VENTX is involved in growth/proliferation/resistance of several cancer cell lines (e.g., brain, pancreatic, renal and ovarian cancers)." (PMID 35892595, 2022). "To explore a potential role of VentX in chemotherapy of solid tumors, we asked whether VentX expression could be induced in cancer cells derived from solid tumors." (PMID 27175592, 2016). "However, we found that, similar to hematological malignancies, VentX expression in cancer cells derived from solid tumors can be induced by chemotherapeutic agents." (PMID 27175592, 2016). "Taken together, our findings suggest that VentX may function as a novel therapeutic target in cancer treatment." (PMID 27175592, 2016). "The robust deterministic process of single-cell cancer induction that we uncovered suggests that the aberrant reactivation of Epi-Driver genes involved in reprogramming/pluripotency (such as VENTX/NANOG, POU5/OCT4) might be relevant to the irreversible malignant transformation of a cell." (PMID 40130618, 2025). "Targeting VentX, therefore, may open novel venue of cancer immunotherapy." (PMID 29872044, 2018). "Here we demonstrate that VentX exerts strong inhibitory effects on the proliferation and survival of cancer cells, but not primary transformed cells, such as 293T cells." (PMID 27175592, 2016). "Mechanistically, consistent with the idea that phagocytosis plays an important role in cancer immune surveillance, the down-regulated VentX expression in TAMs suggested that the lack of an internal drive of TAM for phagocytosis may play an important role in the immune evasion of cancer cells." (PMID 38299030, 2024).
infection (1 paper, 2024). The state of being infected such as from the introduction of a foreign agent such as serum, vaccine, antigenic substance or organism. "TILT-322 infection of ovarian ascites samples led to downregulation of 14 differentially expressed genes (SLC26A4-AS1, APOE, TREM2, CD36, AC145676.1, VENTX, FP671120.4, AC007663.4, AC112220.2, C1QC, TEPP, AC027796.4, AC016026.1, and C1QA) in ascites samples." (PMID 38910324, 2024).
VENTX also shares sentences with these, for which no sentence is quoted: acute myelomonocytic leukemia (1 paper); embryonal carcinoma (1); glioblastoma (1); hematological malignancies (1); kidney cancer (1); lung carcinoma (1); lymphoma (1); polycythemia vera (1); synpolydactyly (1).